MDM2 (MDM2 proto-oncogene)
Diseases named in the same sentence as MDM2 in open-access papers (continued):
Sharing a sentence is not in itself a finding about the gene and the disease.
tumor (continued). "MDM2 and CDK4 amplification is a potential therapeutic target in these tumours with ongoing Phase I and II trials of CDK4 and/or MDM2 inhibitors, but there are no established treatment options developed yet based on these genetic alterations." (PMID 40144205, 2025). "In this case, spindle and stellate tumor cells were strongly positive for vimentin and CD34, and negative for CK, desmin, SMA, HMB-45, MDM2, CDK4, p16, β-catenin, and STAT6." (PMID 41458523, 2025). "Agaimy and his colleagues found that both MDM2 immunohistochemistry and FISH provided a positive result in FDCS, but the CDK4 was negative in the tumor cells." (PMID 38297323, 2024). "On IHC, atypical spindle cell/ pleomorphic lipomatous tumor shows variable positivity for CD34, S100 protein, and desmin, while MDM2 and CDK4 are often negative." (PMID 38916002, 2024). "In particular, if a tumor is located in the deep tissue or imaging findings are not typical, the possibility of ALT should be considered and immunohistochemistry for MDM2 and CDK4 are mandatory." (PMID 39109289, 2024). "Immunohistochemically, the tumor cells were positive for CD-34 and negative for CDK4, MDM2, and p16." (PMID 40777097, 2024). "No immunoreactivity for CK, S100, CD31, ERG, MDM2, CDK4, Melan A, or HMB45 was detected in the tumor cells." (PMID 38388450, 2024). "Amplification of MDM2 and CDK4 genes can be detected in various mesenchymal and nonmesenchymal neoplasms." (PMID 38275873, 2024). "Immunohistochemical analysis demonstrated the positive expression of S100A4, CDK4, MDM2, CD34, and Vimentin, along with the negative expression of Leptin, confirming the tumor’s high aggressiveness and malignancy." (PMID 39591300, 2024). "Immunohistochemically (IHC), tumor cells were positive for SMA, MDM2, and p16; the cells were negative for desmin, MyoD1, Myogenin, pan-cytokeratin, S100, SOX10, HMB45, Malen-A, CD34, CD31, CD99, and ALK." (PMID 37735390, 2023). "The tumor is typically negative for MDM2 and CDK4 or show only focal weak staining, with consistent absence of MDM2 and CDK4 amplification." (PMID 34089125, 2022). "By immunohistochemistry, the tumor cells in both components were immunoreactive for CDK4, but negative for MDM2." (PMID 34089125, 2022). "Tumor cells were nonreactive for SF-1, inhibin alpha, desmin, HHF35, HMB45, Melan A, MITF, c-kit, DOG1, cytokeratin AE1/AE3, h-caldesmon, STAT6, CD68, MDM2, CDK4, c17, DHEAST, 3BHSD, CD31, Factor 8, and ERG." (PMID 34797454, 2021). "In contrast, the tumor cells were nonreactive for SF-1, inhibin alpha, desmin, HHF35, HMB45, Melan A, MITF, c-kit, DOG1, cytokeratin AE1/AE3, h-caldesmon, STAT6, CD68, MDM2, CDK4, c17, DHEAST, 3BHSD, CD31, Factor 8, and ERG." (PMID 34797454, 2021). "The final pathological analysis showed no malignant tumor cells and negative immunohistochemical staining results for CDK4 and MDM2; therefore, ruling out a diagnosis of the low-grade malignant bone tumor." (PMID 33228609, 2020).
tumor (continued). "Pathological analysis revealed no malignant tumor cells, and immunohistochemical staining for CDK4 and MDM2 yielded negative results." (PMID 33228609, 2020). "In the orthotopic model in the present study, both MDM2 and MDMX significantly enhanced the metastatic potential of the MDA-MB-231 cells, but they did not significantly increase the final tumor volume." (PMID 30642351, 2019). "Stable overexpression of Mdm-2, but not Mdm-1 or Mdm-3, in NIH3T3 cells conferred oncogenic potential resulting in enhanced tumour growth." (PMID 31310653, 2019). "Immunohistochemical examination indicates that the tumor cells were diffusely positive for Factor VIII, Fli-1, CDK4, INI-1, MDM2, vimentin, focally positive for AE1/AE3, CD31 and negative for actin-sm, CD34, desmin, myoD1 and S-100." (PMID 26315812, 2015). "The tumor was analyzed by fluorescence in situ hybridization (FISH), and revealed the absence of DDIT3 alteration or MDM2 amplification, thus supporting the diagnosis of DFML and excluding a diagnosis of myxoid liposarcoma." (PMID 25621027, 2015). "In contrast, the levels of naturally processed pMDM100 peptide in the tumor cell lines MBL-2 and C205 were sufficient to induce Ag-specific cytotoxicity by T cells expressing MDM2-TCR but not LoMDM2-TCR, consistent with the activity of the parental clones." (PMID 25539815, 2015). "In IHC, the tumor cells were negative for desmin, S-100, c-Kit, CK-AE1/AE3, EMA, CD31, CD117, CDK4, MDM2 and p63." (PMID 26337721, 2015). "Immunohistochemical studies revealed that the tumor cells was positive for VIM and MDM2, and was negative for CK, MSA, SMA, DES, S-100 and CD34." (PMID 24444015, 2014). "A correlation was also noted between MDM2 antagonist treatment and increased numbers of TUNEL-positive, apoptotic tumor cells; however this failed to reach statistical significance." (PMID 24216990, 2013). "The analysis revealed a significant level of mutual information between the MDM2 SNP309 locus and the age of first tumor onset, but not between gender and the age of tumor onset." (PMID 18398474, 2008). "In rare instances, WDLPS may lack MDM2 amplification, or false-negative FISH results may occur due to limited sampling or low tumor cell content in core biopsies." (PMID 40677885, 2025). "Notably, we found that xenografts only formed from the recurrent tumor harboring the gain of PDGFRA and amplification of CDK4 and MDM2, which were not identified in the initial tumor." (PMID 38012788, 2023). "Positive amplification of the MDM2 gene supports a diagnosis of WDLS; however, a negative biopsy does not exclude the diagnosis due to varied amplification among different cells in the same tumour." (PMID 35355572, 2022).
tumor (continued). "MDM2 expression was observed in 93T449 and 94T778 cells, whereas TAFs had no MDM2 protein expression, suggesting that the purified TAFs did not contain RLPS tumor cells." (PMID 35982904, 2022). "However, currently known senescence scavengers, such as MDM2 inhibitors and BCL-2 family inhibitors, are not cell specific, and, therefore, the removal of senescent anti-tumor immune cells will lead to unpredictable toxic side effects." (PMID 35720278, 2022). "The analysis did not detect MDM2 amplification, Rb1 deletion, break apart signals of EWSR1, FUS, DDIT3, or c-myc, or c-myc-IGH fusion signals, but it did detect more c-myc signals in 837 out of 996 tumor cells and 823 out of 1,000 tumor cells." (PMID 36514176, 2022). "Tumor material from the remaining 7 LMS patients had previously been studied by SNP arrays (a median of 3 tumors per patient) and none of these specimens harbored amplification of the MDM2 locus." (PMID 34986184, 2022). "The tumor is negative for EMA, cytokeratin 7, cytokeratin 20, chromogranin A, synaptophysin, S-100 protein, HMB-45, desmin, SMA, EBV, CD117, DOG1, CD23, CD21, clusterin, MDM2, CD34, D240, and ERG." (PMID 31623602, 2019). "Interestingly, although MDM2 promotes the cancer cell release from the primary tumor into the circulating system, the observed downregulation of CXCR4 or PTGS2 expression by MDM2 knockdown was not statistically significant." (PMID 30642351, 2019). "In contrast to the previous suggestion that MDM2 amplifications may be more likely found in ARMS tumors compared to ERMS, we observed no amplifications in either tumor subtype." (PMID 22550420, 2012). "Interestingly, the MDM2 SNP309 locus and gender taken together were shown to interact and affect the age of non-gender specific tumor diagnosis in a non-additive, synergistic manner (Synergistic Information = 0.06 bits; p = 0.05)." (PMID 18398474, 2008). "Additionally, the tumor was negative for most immunohistochemical markers (CKAE1/AE3, p63, CD23, CD21, MUC4, NUT, CDK4, Pan-TRK, STAT6, SS18, MDM2, Desmin, S100, ERG, TLE1, Fli) and showed only weak and most probably unspecific expression of CD99, CD56, and CD34." (PMID 39519042, 2024). "The PKPD model of HDM201 also demonstrated that the anti-tumor activity of HDM201 was not scheduled dependent, but was related to cumulative dose, suggesting the feasibility of clinical intermittent administration to reduce the common hematological toxicity of MDM2 inhibitors." (PMID 35831864, 2022).
tumor (continued). "MDM2 and CDK4 immunostaining are not specific for diagnosis but could be expressed by tumor cells." (PMID 31299983, 2019). "Interestingly, this analysis revealed that the MDM2 SNP309 locus and gender taken together interact to affect the age of tumor diagnosis in a non-additive, synergistic manner, as demonstrated by the measured 0.06 bits of significant synergistic information (p = 0.05, Permutation Test)." (PMID 18398474, 2008).
cancer (1,767 papers, 1996 to 2026). A tumor composed of atypical neoplastic, often pleomorphic cells that invade other tissues. "We further examine the pathological effects of MDM2 dysregulation and SNPs linked to increased cancer risk." (PMID 41749800, 2026). "MDM2 represents a promising druggable target for the development of novel therapeutic strategies for the treatment of cancer and other diseases where it is implicated, beyond oncology." (PMID 39920118, 2025). "Here, we discuss the existing literature showing how RiBi rate and genomic alterations of ribosomal proteins (RP mutations/deletions) influence the degree of MDM2 inhibition after treatment with RiBi inhibitors in cancer cells." (PMID 41660279, 2025). "In our cohort of patients with PCa, AR, FOXA1, MTOR, and MDM2 showed the highest rate of novel and pathogenic mutations, with 7, 3, 3, and 2, respectively, evidencing their relevance in this type of cancer." (PMID 41009328, 2025). "MDM2 is implicated in E-cadherin ubiquitination and down-regulation, thus promoting cancer cell migration and differentiation." (PMID 39960347, 2025). "An association of MDM2 amplification in 4 HMGA2-overexpressing carcinomas ex PA with particular gear-like nuclear atypia was recently reported, prompting further analysis of the phenomenon in our study." (PMID 40033554, 2025).